HMOX1 (heme oxygenase 1)
Diseases named in the same sentence as HMOX1 in open-access papers (continued):
Sharing a sentence is not in itself a finding about the gene and the disease.
colon carcinoma (83 papers, 2010 to 2026). "More recently, quercetin has been shown to modulate the nuclear factor erythroid 2-related factor (Nrf2)/heme oxygenase-1 (HO-1) pathway to reverse 5-FU resistance in colon cancer cells." (PMID 39061884, 2024). "(Birch Etna) induce ferroptosis by upregulating heme oxygenase-1 (HO-1) expression in a human colon cancer cell line." (PMID 34830285, 2021). "Rottlerin increased HO-1 (heme oxygenase-1) expression via ROS (reactive oxygen species) pathway in human colon cancer cells." (PMID 27626499, 2016). "Although UVC is regarded as a poor activator of the Nrf2 response in some cell types, exposure of HCT116 colon carcinoma cells to UVC (20 J/m2) did cause a marked activation of Nrf2 and transcription of its downstream target heme oxygenase-1 (HO-1), likely by promoting the generation of ROS." (PMID 32796711, 2020). "Analysis of human colon tumor tissue revealed decreased expression of IRP-1, HMOX-1, and FTH1 but increased HAMP expression." (PMID 39097854, 2024). "We identify multiple genes that are upregulated due to loss of post-transcriptional suppression after inhibition of miR-24-3p, most notably HMOX1 and PRSS8, which are also prominently downregulated in TCGA colon tumors." (PMID 36457077, 2022). "Previous analyses of the transcriptional response to VLX1570 in colon cancer cells and AML cells are similar to that of proteasome inhibitors, showing the induction of chaperones, heme oxygenase-1, and immediate early-response genes." (PMID 34572552, 2021). "In vitro studies also showed augmented expression of HMOX1 in primary colon cancer tissues and HCT116 colon cancer cells compared with normal surrounding tissue and with normal epithelial cell line, respectively." (PMID 30258436, 2018). "In silico analysis further supported these observations; in that, the expression of IRP-1, HMOX-1, and FTH1 expression was significantly decreased while that of HAMP (Hepcidin) was significantly increased in primary colon tumor tissue compared to normal tissue." (PMID 39097854, 2024). "In the present study, we showed that the induction of senescence in colon cancer cells led to the upregulation of two enzymes involved in H2O2 utilization, catalase, and glutathione peroxidase-1 but the downregulation of heme oxygenase-1, heme degrading enzyme." (PMID 36230727, 2022). "The Nrf2 target genes, such as heme oxygenase-1 (HO-1) and NAD(P)H-quinone oxidoreductase-1 (NQO1) are reported to mediate chemotherapy resistance in several cancers, including gastric and colon cancers." (PMID 34249773, 2021).
endothelial dysfunction (83 papers, 2011 to 2026). In vascular diseases, endothelial dysfunction is a systemic pathological state of the endothelium (the inner lining of blood vessels) and can be broadly defined as an imbalance between vasodilating and vasoconstricting substances produced by (or acting on) the endothelium. "Mechanistic studies indicated that NAT10 facilitated the N4-acetylcytidine modification of HMOX1 (heme oxygenase 1), which enhanced its mRNA stability, leading to the accumulation of ferrous ions, and exacerbating endothelial dysfunction in DVT." (PMID 41467352, 2026). "All these data suggest that inhibition of NAT10 reduces HMOX1 expression and attenuates ferroptosis, thereby mitigating endothelial dysfunction and the formation of thrombosis in DVT mice." (PMID 41467352, 2026). "Together, these data indicated that inhibition of NAT10 reduced HMOX1 expression and alleviated ferroptosis, thereby attenuating endothelial dysfunction." (PMID 41467352, 2026). "Mechanistic analysis revealed enhancements in NO bioavailability and increased heme oxygenase-1 (HO-1) expression, contributing to its protective effects against oxidant-induced endothelial dysfunction." (PMID 41394126, 2025). "Heme-oxygenase-1 catalyzes the degradation of heme to carbon monoxide and bilirubin, which also have cytoprotective effects for endothelial dysfunction against various stresses." (PMID 38069389, 2023). "Clinically observed adverse effects and toxicological studies have identified elevation of oxidative stress as the main mechanism of IDX-induced endothelial dysfunction, and heme oxygenase-1 is up-regulated to counteract the injury." (PMID 36812321, 2023). "Beta-blocker treatment mitigated inflammatory changes occurring after endothelial dysfunction and promoted cytoprotective antioxidant heme oxygenase-1." (PMID 34362171, 2021). "Recent studies have indicated that endoglin can inhibit NO and heme oxygenase-1 (HO-1) synthesis and reduce production of CO and bilirubin, thereby leading to endothelial dysfunction, blood pressure elevation and development of severe preeclampsia." (PMID 27736929, 2016). "Recent studies demonstrate that galangin attenuates endothelial dysfunction by activating the heme oxygenase-1 (HO-1) signaling pathway, reducing oxidative stress, and suppressing proinflammatory mediators such as VCAM-1 and TNF-α in vascular endothelial cells." (PMID 40867855, 2025). "As such, targeted studies exploring the mechanism by which HMOX1 influences these receptors and the functional consequence of those changes could illuminate potential therapeutic targets for endothelial dysfunction and vascular diseases." (PMID 34595164, 2021). "In vascular cells, the role of HMOX1 is protective in endothelial dysfunction." (PMID 35071238, 2021). "PE-DBMSCs with decreased HMOX1 expression as observed in this study justifiably show decreased functional consequences, and they may be a contributing factor for endothelial dysfunction." (PMID 31964423, 2020). "Thus, the careful modulation of HMOX1 activity and bilirubin generation offers a promising target in the context of prevention and treatment of endothelial dysfunction but also with an aim to ensure healthy aging." (PMID 32082188, 2020). "Supplementation of SAM could inhibit proliferation and migration of VSMCs and reduce carotid intima thickness by reducing the inflammatory process and reducing endoplasmic reticulum and oxidative stresses and prevent endothelial dysfunction by inducing heme oxygenase-1 expression." (PMID 35277077, 2022). "Also, by studying endothelial dysfunction, the absence of Nox4 resulted in reduction of endothelial nitric oxide synthase expression, nitric oxide production, and heme oxygenase-1 expression, which was associated with apoptosis and inflammatory activation." (PMID 25880434, 2015).
endothelial dysfunction (continued). "Collectively, these findings identify MALAT1 as a protective regulator that mitigates endothelial dysfunction, vascular remodeling, and PH in SCD, at least in part through the induction of HMOX1." (PMID 41597229, 2026). "A decrease in GSH and 3-nitrotyrosine levels and reduced expression of both Nrf2/ARE and heme oxygenase-1 (HO-1) pathways, as well as glutamate-cysteine ligase catalytic (GCLC), have been demonstrated in endothelial dysfunction of young smokers." (PMID 35268723, 2022). "As both increasing plasma levels of bilirubin and up-regulating HMOX1 could lead to toxic effects, the discovery of new strategies to reduce its toxic potential to maintain therapeutic effectiveness will be key for the treatment/prevention of endothelial dysfunction." (PMID 32082188, 2020). "Specifically, the heme oxygenase-1 (HO-1), NADPH quinone oxidoreductase (NQO-1), glutamate-cysteine ligase catalytic subunit (GCLC), Phospho-Akt (p-Akt), and Phospho-eNOS (p-eNOS) expression levels were enhanced by sinapic acid, easing endothelial dysfunction." (PMID 38611326, 2024). "While the activation of HMOX1 has been observed as early as 2 h post-stress and in late-stage disease models, its role in the transition from early to late endothelial dysfunction has not been explored." (PMID 34595164, 2021).
liver fibrosis (80 papers, 2011 to 2026). "Another study found that the hepatoprotective effects of pomegranate extract and curcumin against thioacetamide-induced liver fibrosis are linked to their ability to modulate the Nrf2/heme oxygenase-1 (HO-1), NF-κB, and TGF-β/Smad3 signaling pathways." (PMID 40647314, 2025). "Concurrently, a series of antioxidant systems are activated, and excessive ROS can activate the nuclear factor E2-related factor-2/heme oxygenase-1 (Nrf2/HO-1) signaling pathway, exerting antioxidant effects and alleviating liver fibrosis." (PMID 39689154, 2025). "Contrary to its recognized role in antioxidant defense, it has been reported that HMOX-1 promotes ferroptosis of hepatic stellate cells and thus affects the progression of liver fibrosis." (PMID 39309491, 2024). "This excessive iron accumulation enhances ferroptosis in hepatocytes by inducing heme oxygenase-1 (HO-1) expression, which contributes to the progression of liver fibrosis, accompanied by the upregulation of FGF21 protein levels in vitro and in vivo." (PMID 37860583, 2023). "Such excessive iron accumulation enhanced ferroptosis in hepatocytes by inducing heme oxygenase 1 (HO-1) expression, which contributed to the progression of liver fibrosis, accompanied by the upregulation of the FGF21 protein level in vitro and in vivo." (PMID 36703745, 2022). "The induction of heme oxygenase-1 (HO-1) has been shown to have therapeutic potential in experimental models of hepatitis and liver fibrosis, which are closely related to liver cancer." (PMID 33916685, 2021). "Hmox1, who is reported as an anti-fibrogenetic protein in liver fibrosis, also functions as a modulator of inflammation and enhances autophagy." (PMID 31514486, 2019). "On this basis, we further verified whether XSJ improved liver fibrosis through the PI3K/AKT/Hmox1 pathway via Western blotting experiments." (PMID 41484887, 2026). "Additionally, iron homeostasis is linked to liver fibrosis, and XSJ reversed the expression of related genes (Hmox1, Hamp, Hamp2)." (PMID 41484887, 2026). "Overexpression of Hmox1 can catalyze the degradation of heme, releasing iron ions, which in turn trigger ferroptosis, thereby exacerbating the pathological process of liver fibrosis." (PMID 41484887, 2026). "Therefore, abnormal activation of the PI3K/AKT/Hmox1 pathway may play a critical role in the development of liver fibrosis, suggesting that it could serve as a novel therapeutic intervention target." (PMID 41484887, 2026). "Notably, protein–protein interaction (PPI) network analysis, which combined the results of network pharmacology and transcriptomics, revealed that the PI3K/AKT and Nrf2/Hmox1 pathways might be closely related to liver fibrosis induced by CDAHFD." (PMID 41484887, 2026). "Magnesium isoglycyrrhizinate (MgIG) can upregulate heme oxygenase 1 (HO-1) expression, leading to intracellular iron deposition, lipid peroxide accumulation, the induction of ferroptosis in HSC, and the inhibition of liver fibrosis." (PMID 37007035, 2023). "Additionally, XSJ suppressed the progression of liver fibrosis by inhibiting the TGF-β1/Smads and PI3K/AKT/Hmox1 signaling pathways." (PMID 41484887, 2026). "Moreover, XSJ attenuated the progression of liver fibrosis by inhibiting the TGF-β1/Smads and PI3K/AKT/Hmox1 signaling pathways." (PMID 41484887, 2026). "Long-term ingestion of APAP can induce liver fibrosis, while andrographolide has been shown to alleviate APAP-induced liver fibrosis in mice by activating Nrf2 and upregulating the expression of downstream genes glutamate-cysteine ligase (GCLC and GCLM) and heme oxygenase-1 (HO-1)." (PMID 40959446, 2025). "Enhancement of the activities of some antioxidant enzymes such as catalase (CAT), glutathione reductase (GR), glutathione peroxidase (GPx), heme oxygenase 1 (HO-1), and superoxide dismutase (SOD) can inhibit oxidative stress and thereby delay the development of liver fibrosis." (PMID 33029279, 2020).
myocardial infarction (79 papers, 2009 to 2026). Gross necrosis of the myocardium, as a result of interruption of the blood supply to the area, as in coronary thrombosis. "The increase of SLC2A3, EPAS1 and HMOX1 were risk factors for myocardial infarction, while ATM and FANCD2 were protective factors." (PMID 38253721, 2024). "A (GT)n dinucleotide repeat and a -413A>T single nucleotide polymorphism have been reported in the promoter region of HMOX1 to both influence the occurrence of coronary artery disease and myocardial infarction." (PMID 19389234, 2009). "Induction of the antioxidant enzyme heme oxygenase-1 (HO-1) affords cellular protection and suppresses proliferation of vascular smooth muscle cells (VSMCs) associated with a variety of pathological cardiovascular conditions including myocardial infarction and vascular injury." (PMID 24744106, 2015). "Elevated bilirubin levels have also been shown to be closely related to the levels of heme oxygenase-1 (HO-1), a stress-related enzyme, in patients with acute myocardial infarction (AMI)." (PMID 40364067, 2025). "SLC2A3, EPAS1, HMOX1, ATM and FANCD2 genes all had good diagnostic value for myocardial infarction (P < 0.05)." (PMID 38253721, 2024). "During the early and intermediate phases of myocardial infarction, Hmox1 activity is reportedly enhanced and mediated by the Nrf2/Hmox1 axis, which promotes iron overload and leads to ferroptosis in myocardial cells." (PMID 37181809, 2023). "Overexpression of heme oxygenase-1 (HO-1)-MSCs mediates cardiac protection and functional improvement through a paracrine mechanism in a rat model of myocardial infarction." (PMID 35008675, 2021). "The increase of SLC2A3, EPAS1 and HMOX1 are risk factors for myocardial infarction, while ATM and FANCD2 are protective factors.Decision tree analysis showed that SLC2A3, HMOX1, ATM, FANCD2 gene had higher net yield in diagnosing myocardial infarction." (PMID 38253721, 2024). "ROC curves of 5 different genes related to ferroptosis associated with myocardial infarction showed that SLC2A3, EPAS1, HMOX1, ATM and FANCD2 genes had good diagnostic value for myocardial infarction, and the elevation of SLC2A3, EPAS1 and HMOX1 was a risk factor for myocardial infarction." (PMID 38253721, 2024). "ROC curves of 5 differentially ferroptosis-related genes associated with myocardial infarction showed that SLC2A3, EPAS1, HMOX1, ATM and FANCD2 genes had good diagnostic value for myocardial infarction, and the area under the curve had statistical significance (P < 0.05)." (PMID 38253721, 2024). "Multiple animal studies have reported the upregulation of HMOX1 in atherosclerosis and myocardial infarction (MI)." (PMID 36293289, 2022). "Cardioprotective effects of Hmox1 were demonstrated in experimental models of myocardial infarction (MI)." (PMID 28534119, 2017). "According to the method of systematic random sampling, the sample size was divided into test set and verification set, and the decision tree model of SLC2A3, EPAS1, HMOX1, ATM and FANCD2 genes on myocardial infarction was established." (PMID 38253721, 2024). "The results showed that SLC2A3, HMOX1, ATM and FANCD2 genes had higher net yield in the diagnosis of myocardial infarction." (PMID 38253721, 2024).
asthma (77 papers, 2008 to 2025). "A cohort study found that the effect of HMOX-1 gene variants on the risk of new-onset asthma varies with environmental ozone levels." (PMID 35450107, 2022). "The GA and AA genotypes, the A allele, at HMOX1 gene rs17878790 locus increase the risk of asthma." (PMID 40433469, 2025). "Heme oxygenase-1 (HO-1) is an isoform of heme oxygenase enzyme which is linked with asthma." (PMID 40421046, 2025). "Abnormal expression of TIPE2 may inhibit M1 macrophage‐associated neutrophilic inflammation in asthma by targeting the Nrf2/HMOX1 pathway." (PMID 39644500, 2024). "The underlying key genes in asthma pathogenesis and those regulated by treatment including Adipoq, HMOX1, SPP1, Cyp2e1, TNC, MB, MPO, Col9a1, Ckmt2, and Erbb4 were taken as examples to illustrate the positions and relationships with other points and midline in the figure." (PMID 33531915, 2021). "Indeed, in earlier studies in individuals with asthma a strong association was reported between raised levels of exhaled CO and severity of pulmonary disease with an increased expression of heme oxygenase-1 in airway macrophages, interpreted to be due to oxidative stress." (PMID 24622422, 2014). "The age-stratified analysis showed that the asthma risk effects of GSTP1 rs1695, rs4891, CAT rs7943316, and HMOX1 rs17878790 were more significant in the >6-year-old group." (PMID 40433469, 2025). "This study identified significant associations between childhood asthma susceptibility and multiple SNPs in key antioxidant genes (GSTP1, HMOX1, and CAT), suggesting their potential utility as predictive biomarkers." (PMID 40433469, 2025). "Binary logistic regression analysis of associations between SNPs of GSTP1, HMOX1, CAT, EPHX1 gene and asthma." (PMID 40433469, 2025). "Researchers including Jiajia Lv found that HMOX1 protects airway epithelial cells of asthma patients from apoptosis." (PMID 40433469, 2025). "Analysis of the biomarker-disease network map revealed that ALOX5, HMOX1, and PLA2G7 were strongly associated with asthma." (PMID 41030501, 2025). "Currently, there is limited research on the correlation between HMOX1 gene SNP loci and asthma onset." (PMID 40433469, 2025). "Among the noteworthy signaling pathways in asthma research, the nuclear factor-erythroid 2-related factor 2 (Nrf2) and heme oxygenase-1 (HO-1) have attracted considerable attention." (PMID 39539452, 2024). "The adenosine 5'‐monophosphate‐activated protein kinase (AMPK)/Sirtuin 1 (Sirt1) and nuclear factor‐E2‐related factor 2 (Nrf2)/Heme oxygenase‐1 (HO‐1) pathways relate closely with development of asthma." (PMID 34342160, 2021). "The antioxidant signaling molecules, nuclear factor erythroid-derived 2-related factor 2 (Nrf2) and heme oxygenase-1 (HO-1), have been targeted by many researchers to counter excessive ROS during asthma development." (PMID 31991647, 2020). "Age-stratified analysis of associations between SNPs of GSTP1, HMOX1, CAT, EPHX1 gene and asthma." (PMID 40433469, 2025). "ALOX5, HMOX1, and PLA2G7 are genes that have been implicated in asthma." (PMID 41030501, 2025). "Antioxidant enzyme defense systems (including SOD, CAT, GPx, reduced glutathione and heme oxygenase 1) are directly regulated by Nrf2, which becomes a potential therapeutic target in lung diseases such as Idiopathic Pulmonary Fibrosis, asthma, COPD and acute respiratory distress syndrome." (PMID 36421423, 2022). "Recently, heme oxygenase-1 (HO-1) was shown to be induced in the airways of patients with asthma." (PMID 27478309, 2016). "Previous studies have demonstrated that genes involved in oxidative stress response, including GSTP1, CAT, HMOX1, and EPHX1, participate in the pathogenesis of asthma." (PMID 40433469, 2025). "HMOX1, ITGAM, DDX58, SFTPD and ADAM17 were the top novel targets identified for asthma which needs to be validated experimentally." (PMID 37735578, 2023).